CXCR4 (C-X-C motif chemokine receptor 4)
Diseases named in the same sentence as CXCR4 in open-access papers (continued):
Sharing a sentence is not in itself a finding about the gene and the disease.
breast carcinoma (continued). "For instance, CXCL12 and SLC (CCL-21) bind to CXCR4 and CCR7 receptors on breast cancer cells, respectively, promoting tumor cell migration to the lymphatic system along a chemotactic gradient." (PMID 40084140, 2025). "By employing UALCAN, we examined the pattern of expression for TGFβ-1, IL19, CXCR4, BMP1, VCAN, and WNT2 in breast cancer." (PMID 41348904, 2025). "NOB can downregulate CXCR4 and MMP-9 as well as the activity of MMP-9 by inhibiting NF-κB and activating MAPKs, thereby reducing the invasion of breast cancer cells." (PMID 41425709, 2025). "Chemokine receptor 4 (CXCR4), the receptor of chemokine CXCL12/SDF-1 (stromal cell-derived factor-1) has been identified as a potential target for breast cancer imaging and therapy." (PMID 40075611, 2025). "In basal-like breast cancer, the expression of chemokine CXCL12 and its receptor CXCR4 is increased significantly under hypoxic environment compared to other BC subtypes, which increases the degree of infiltration of CD4+T cell subsets with significant immunosuppressive effect, such as Tregs." (PMID 40438111, 2025). "CXCR3 and CXCR4 play crucial roles in mobilizing Treg cells to tumor locations in various cancers, including ovarian cancer, hepatocellular carcinoma (HCC), breast cancer, and lymphoma." (PMID 39000453, 2024). "Future studies will be needed to determine the best practice and compounds for the simultaneous inhibition of the CXCL12/CXCR4 axis and the MDM2/MDMX axis to block breast cancer metastasis." (PMID 39766093, 2024). "Again, in breast cancer, ACKRs that scavenge CXCL12 limited tumor growth and metastasis in CXCR4+ breast cancer cells possibly due to reduced neovascularization or disruption of CXCL12-guided egress through tumor-associated lymphatic vessels." (PMID 38786066, 2024). "In breast cancer, bioinformatic analysis indicated that BACH1 mediates four Bone Marrow Signature (BMS) genes, including MMP1, CXCR4, FHL1, and DUSP1." (PMID 38321558, 2024). "Inhibition of either CXCR4 or JAK2 suppresses STAT3 phosphorylation, reversing the proliferative and metastatic phenotypes of breast cancer." (PMID 38920657, 2024). "In breast cancer, the METTL3-METTL14 complex upregulates the expression of genes like Bcl-2 and CXCR4 through m6A-dependent mechanisms, thereby fostering breast cancer growth and metastasis." (PMID 38965238, 2024). "CXCR4, one of the most prominent chemokine receptors secreted by breast cancer cells and attracted by its ligand, SDF-1cy, is essential for targeted breast cancer metastasis." (PMID 38956273, 2024). "Similar observations regarding high expression of CXCR4 and JUNB were noted in our prior investigations involving metastatic and early breast cancer patients, as well as in NSCLC patients." (PMID 38727318, 2024). "In breast cancer, the CXCL12/CXCR4/ACKR3 axis promoted breast cancer metastasis through the activation of the STAT3 pathway." (PMID 38920657, 2024). "ORL inhibits angiogenesis (VEGF, MMP-9, and CXCR4/CXCL12) and fatty acid synthesis (ACLY, ACC, and FASN) genes and protein expression with the induction of apoptotic genes in different breast cancer cell lines." (PMID 38256929, 2024). "BACH1 is repressed by RKIP, which targets let-7, thereby inhibiting breast cancer bone metastasis by downregulating the expression of BMS genes, including MMP1, OPN, and CXCR4." (PMID 38321558, 2024). "OPN induces stemness by interacting with CD44 BCSCs express higher level of CXCR4, stimulation of CXCR4 signaling by SDF-1 induces mammosphere forming capacity and anoikis-resistance in breast cancer cells." (PMID 39238997, 2024). "Further investigations reveal that the CXCL12/CXCR4 axis phosphorylates JAK2, thereby activating the STAT3 signaling pathway to promote breast cancer proliferation and metastasis." (PMID 38920657, 2024).
breast carcinoma (continued). "This was further substantiated by decreased bone metastasis of breast cancer cells upon inhibition of CXCL12/CXCR4 axis and indoleamine 2,3-dioxygenase (IDO1) expression." (PMID 39497943, 2024). "In a variety of tumor cells, including gastric cancer, glioblastoma, and breast cancer, the activation of the CXCL12/CXCR4 axis has been observed to stimulate the SRC, ERK, and STAT3 pathways." (PMID 38920657, 2024). "Among all known chemokine receptors, chemokine receptor 4 (CXCR4) and chemokine receptor 7 (CCR7) display a relatively high expression in breast malignant tumors and metastatic tissues." (PMID 38549934, 2024). "In breast cancer cell lines, a positive correlation between COL1A1 and CXCR4 has been observed; specifically, knocking down COL1A1 reduced CXCR4 mRNA expression as compared to wild type cells." (PMID 37373151, 2023). "Taken together, these results indicated that combined targeting CXCR4 with AMD3100 and docetaxel is a potential novel combination therapy for HER2 + breast cancer with trastuzumab resistance." (PMID 37280713, 2023). "For instance, in addition to the CXCL12-CXCR4/CXCR7 signal axis, CXCR4 and CXCR7 significantly reduced the invasion and metastasis in breast cancer mice." (PMID 37497001, 2023). "Chemokine (C-X-C motif) receptor type 4 (CXCR4) and its ligand, chemokine (C-X-C motif) ligand type 12 (CXCL12), are relatively highly expressed in invasive breast cancer cells, homing them to distant lymph nodes, the lungs, and the liver." (PMID 36612320, 2023). "As expected, we also found that the aggressive breast cancer cell lines MDA-MB-231 and 4T1 exhibited higher CXCL12/CXCR4 levels than did MCF 10A normal epithelial breast cells." (PMID 37760498, 2023). "By comparing gene expression between different sublines of human breast cancer cell line MDA-MB-122, researchers identified four highly overexpressed genes in the bone metastasis group: IL11, CTGF, CXCR4, and MMP-1." (PMID 38041134, 2023). "As curcumin exhibited an inhibitory effect on the CXCL12/CXCR4 axis and the NF-κB signaling pathway in MCF7 cells, it was demonstrated that curcumin has the potential to modulate breast cancer TME by repressing both ADMSCs and cancer cells." (PMID 38004606, 2023). "CXCR4 is widely overexpressed in various cancer cells, including MDA-MB-231 breast cancer cells, 8505C thyroid cancer cells, Hs766t pancreatic cancer cells, Jurkat T cells, and U937 and THP-1 monocytic leukemia cells." (PMID 37749552, 2023). "Among the signaling molecules involved with MSC migration to the tumor site are CXCL12/CXCR4, CCL2 in Breast cancer, and SDF-1 in colorectal, prostate, and breast cancers." (PMID 36674525, 2023). "It was suggested that curcumin disrupts the positive feedback loop mediated by CXCL12/CXCR4/NF-κB/SHH between CAFs and MCF7 cells, exhibiting its therapeutic potential by regulating the breast cancer TME." (PMID 38004606, 2023). "Our findings support CXCR4 as a novel therapeutic target and a predictive biomarker for trastuzumab resistance in HER2+ breast cancer." (PMID 37280713, 2023). "Cell surface expression of CXCR4 and the SDF-1α-mediated migration were enhanced in breast cancer cells isolated from mammary fat pad xenografts compared with parental cells grown in culture." (PMID 36701089, 2023). "We observed that CXCR4 forms heteromers with LPA1 in recombinant HEK293A cells and the human breast cancer cell line MDA-MB-231." (PMID 37749552, 2023). "A dipeptidyl peptidase (DPP)-4 inhibitor accelerated breast cancer metastasis by inducing EMT through CXCL12/CXCR4/mTOR axis, while metformin countered the harmful effect of DPP-4 inhibitor on breast cancer metastasis." (PMID 37497001, 2023). "DPP-4 suppression augmented CXCL12/CXCR4 levels, which led to autophagy and HIF-1α in breast cancer cells; a CXCR4 inhibitor reversed these DPP-4 inhibition-induced alterations." (PMID 37760498, 2023).
breast carcinoma (continued). "Our studies above demonstrated that the CXCR4 antagonist AMD3100 inhibits proliferation and survival of HER2 + breast cancer cells with primary or acquired trastuzumab resistance." (PMID 37280713, 2023). "K14+ breast cancer cells expression DDR2 and CXCR4 and CAFs expressing DDR2 guides metastasis from primary tumor organoids to polarize to the leading edge and direct migration." (PMID 36906534, 2023). "DPP-4 knockdown significantly promoted the levels of CXCL12, CXCR4, phospho-mTOR, and HIF-1α in breast cancer cell lines." (PMID 37760498, 2023). "In a co-cultured model of breast cancer cells with MSCs, it has been reported that the migratory capacity of cancer cells increases through the ER-SDF-1/CXCR4 pathway." (PMID 38022534, 2023). "In breast cancer cells, angiopoietin-like protein 2 (ANGPTL2) was found to upregulate CXCR4 and promote bone metastasis in an intracardiac bone metastasis mouse model." (PMID 37025604, 2023). "In contrast to findings described in breast cancer, in MCL and CLL cells CXCR4 was still internalized even when CXCR4, CB1 and CB2 were stimulated simultaneously by their endogenous ligands." (PMID 36900374, 2023). "The increased level of CXCR4 and its canonical ligand CXCL12 (SDF-1α) is frequently found to be elevated in metastatic sites of many cancers, including breast cancer, pancreatic cancer, or cervical/ovarian carcinoma." (PMID 37853467, 2023). "In pancreatic and breast cancer, the polarization and recruitment of M2 macrophages is regulated by the POU1F1/CXCL12/CXCR4 signaling axis to promote tumor metastasis." (PMID 37415241, 2023). "In a model of breast cancer, it has been detected that cancer cells can stimulate the recruitment of BM-MSCs to tumor sites through the SDF-1α/CXCR4 axis." (PMID 38022534, 2023). "Our findings therefore demonstrated that CXCR4 is a promising therapeutic target and a predictive biomarker in HER2 + breast cancer with trastuzumab resistance." (PMID 37280713, 2023). "For example, in a mouse model of breast cancer with lung metastasis, the chemokine receptor, CXCR4, and its ligand, CXCL12, control the metastasis of the breast cancer cells, where the expression of CXCL12 is high in breast cancer cells." (PMID 37251542, 2023). "The inhibition of CXCR4 reduced growth, migration, and invasion in mouse models carrying breast cancer, and the anti-tumor effect of PARP1 inhibitors was also enhanced when CXCR4 was inhibited." (PMID 37550554, 2023). "Specifically, PYK2 ablation inhibits Notch1 signaling and consequently reduces CCL2 secretion by breast cancer cells, and concurrently reduces the levels of CCR2, CXCR4, IL‐4Rα, and Stat6 activation in macrophages." (PMID 35092356, 2022). "The absorption of the EVs—produced by breast carcinoma cells—by neutrophils increases the expression of IL-8, VEGF, arginase 1, MMP9, and CXCR4 (CD184), which are the main markers for N2 neutrophils." (PMID 36555469, 2022). "On the other hand, miR-218 increased the expression of bone sialoprotein (BSP), osteopontin (OPN), and a chemokine receptor, CXCR4, in MDA-MB-231 breast cancer cells, suggesting that miR-218 supports osteomimicry and, thus, breast cancer cells homing to bone." (PMID 35158995, 2022). "In breast cancer, PI3-kinase, act as key regulatory components involved in CXCR4 induced chemo-invasion." (PMID 36103228, 2022). "Several other studies reported that TCDD inhibited growth or invasiveness, decreasing pro-invasion genes (CXCR4 and MMP-9) in breast cancer cells and 2,3,7,8-tetrachlorodibenzofuran (TCDF) also inhibited invasion of MDA-MB-431 and T47D cells and BT474 cells." (PMID 36428667, 2022). "Both CXCR4 and ACKR3 signaling pathways promote tumor growth and metastasis in breast cancer and multiple other malignancies, making these receptors potential targets for therapy and molecular imaging." (PMID 35681470, 2022).
breast carcinoma (continued). "CXCL12 can stimulate and induce the expression of CXCR7 as well as CXCR4 and various EMT markers in human breast cancer cells." (PMID 36077241, 2022). "The depletion of FAM189A2 in breast cancer cells prohibits the CXCL12‐stimulated endocytosis of CXCR4 and, importantly, enhances the cellular function of CXCR4 for the cell migration and stemness." (PMID 34927784, 2022). "In a murine breast cancer model, primary tumors induce B cell accumulation in draining lymph nodes and foster metastasis through activation of the CXCL12/CXCR4 axis." (PMID 35565443, 2022). "In breast cancer, CXCL12/CXCR4-dependent cell migration plays an important role in progression, for which AQP3 is crucial through H2O2 transport via channel activity from AQP3." (PMID 35847914, 2022). "Interaction of the chemokine receptors CXCR4 with β-arrestin 2 enhances stromal cell-derived factor 1α-induced activation of p38 MAPK and ERK, thereby augmenting lymphocyte and breast cancer chemotaxis." (PMID 36010884, 2022). "Metastatic breast cancer cells overexpress the chemokine receptor CXCR4, and metastatic tissues express a large amount of CXCL12, a ligand of CXCR4." (PMID 36012631, 2022). "A CXCR4 antagonist (cyclam monomer) combined with a CD44 inhibitor (Star miR-34a) demonstrated antitumour and antimetastatic efficacy in breast cancer." (PMID 35468838, 2022). "There were seven shared hub nodes (FPR2, CXCR4, FPR1, CX3CL1, GPR37, GABBR2 and PLCB1) between metastatic breast cancer cell lines." (PMID 35045088, 2022). "In particular, we show that the OHD4–12 binds and activates the CXCL12 receptor CXCR4 and inhibits the CXCL12-driven migration of MDA-MB-231 breast cancer cells." (PMID 36229490, 2022). "LIP was furthermore shown to upregulate the expression of the chemokine receptor CXCR4 and the pro-invasive CDH3/P cadherin in breast cancer cells, both known drivers of metastasis." (PMID 35042889, 2022). "In highly invasive cells, such as MDA-MB-231 breast cancer cells, the binding of CXCL12 to CXCR4 activates multiple downstream signaling pathways, including calcium mobilization." (PMID 36229490, 2022). "Compared to CXCR4 low/CD62L high immature neutrophils, aged neutrophils facilitate breast cancer migration and mediate metastasis through increased release of neutrophil extracellular traps." (PMID 35464064, 2022). "Probably due to decreased CXCL12 cleavage, DPP-IV ablation promoted epithelial–mesenchymal transition, breast cancer metastasis, and the upregulation of ABC transporters via the CXCL12/CXCR4/mTOR axis." (PMID 35565202, 2022). "pAKT levels are elevated in 81.8% of primary HER2-positive breast cancers with bone metastasis, suggesting that the HER2/CXCR4/AKT pathway plays a role in bone metastasis." (PMID 36012631, 2022). "KDM6A physically interacts with ERα upon E2 treatment, demethylates H3K27me3 to facilitate the expression of C-X-C Motif Chemokine Receptor 4 (CXCR4) oncogene or the pluripotency factors NANOG, SOX2, and KLF4, which are related to breast cancer metastasis." (PMID 35453496, 2022). "Enhanced CXCR4 and ACKR3 levels in breast cancer compared to normal tissues has been reported, although their relative abundance within molecular subtypes and in BC cellular models is unclear." (PMID 36233192, 2022). "FAM189A2‐knockout prohibits CXCL12‐induced endocytosis of CXCR4, thereby enhancing the effects of CXCL12 on the chemotaxis and mammosphere formation of breast cancer cells." (PMID 34927784, 2022). "In breast cancer, the stability and expression of METTL14 are positively regulated by LNC942, which elevates the m6A content in downstream targets CXCR4 and CYP1B1, stabilizes protein expression and translation, and further promotes tumorigenesis." (PMID 34904301, 2022). "We observed dose-dependent cAMP inhibition after the stimulation of cells with either ligand, demonstrating that CXCR4 and CCR7 are functionally active in advanced human breast cancer cells." (PMID 34685420, 2021).
breast carcinoma (continued). "We demonstrate here that the CXCR4 and CCR7 receptor ligands, CXCL12 and CCL19, cooperatively bind and selectively elicit synergistic signalling responses in invasive breast cancer cell lines as well as primary mammary human tumour cells." (PMID 34685420, 2021). "Here, we demonstrate the important roles of the CXCR4 and P2Y11 purinergic receptors in mediating the inhibitory effect of ATP on breast cancer cell migration and bone metastasis." (PMID 34503103, 2021). "In the CXCR4-positive Tregs, tumoral CXCL12 enhances recruitment and suppresses the anti-tumor immune response in basal-like breast cancer." (PMID 33937018, 2021). "In the breast cancer cell line MDA-MB-435, 5-aza-CDR reversed CXCR4 gene promoter hypermethylation, leading to a consecutive increase in CXCR4 expression." (PMID 33671498, 2021). "In breast cancer, the CXCL12/CXCR4 axis has been extensively investigated in regard to the homing of cancer cells to metastatic sites and promoting metastasis." (PMID 34427969, 2021). "To determine if CXCR4 and CCR7 heterodimerization are relevant to the development of human breast cancer, we took advantage of the proximity ligation assay (PLA), a well-established method for determining in situ protein-protein interactions." (PMID 34685420, 2021). "Inhibition of CXCR4 signaling decreases desmoplasia and reprograms the suppressive TIME of metastatic breast cancer, thus delaying the growth of metastatic tumors and improving survival in an animal model." (PMID 34112258, 2021). "Many members of the Gi/o-GPCR family, such as LPAR, CXCR4, CXCR7, and PAR1, play a role in breast cancer progression." (PMID 34343132, 2021). "Previous studies have shown that the positive-feedback loop initiated by the C-X-C chemokine receptor type 4 (CXCR4), highly expressed in malignant BCCs, to the CXCL12 expressed in bone lead to breast cancer migration." (PMID 34754042, 2021). "Compared with other subtypes of breast cancer, CXCR4 expression was specifically raised in the TNBC patients; the high expression level of CXCR4 predicted a high malignant grade and a high possibility of recurrence." (PMID 33875646, 2021). "Radiotracer 9 was then utilized in a couple of other studies to image CXCR4 in tumor models, such as Waldenström Macroglobulinemia, brain tumor xenografts, and lung metastases derived from MDA-MB-231 breast cancer cells." (PMID 34500609, 2021). "Studies have shown that CXCR4 mediates MMP12 to degrade the matrix, leading to breast cancer infiltration and growth." (PMID 35069702, 2021). "Our observations thus provide the first clear evidence for a specific novel link between the CXCR4-CCR7 heterodimerization, CXCR4 and CCR7 function and the metastatic propensity of breast cancer cells." (PMID 34685420, 2021). "Likewise, the chemokine receptor CXCR4 has multiple upstream mediators, with upregulation in renal cell carcinoma described in response to hypoxia inducible factor (HIF1a) and galectin 1, and in breast cancer with angiotensin II type I receptor (AGTR-1) and NF kappa B." (PMID 33927349, 2021). "The chemokine CXCL12 and its receptor, CXCR4 and CXCR7, play an important role in breast cancer growth and metastasis." (PMID 35111484, 2021). "While CXCR4, together with its ligand CXCL12, has been investigated in the mechanisms of breast cancer progression through angiogenesis, EMT, and immunosuppression." (PMID 34611125, 2021). "LINC00942 was reported to promote METT14-mediated M6A methylation and regulate the expression and stability of its target gene CXCR4 and CYP1B1 during the initiation and progression of breast cancer." (PMID 34760693, 2021). "Here, they formulated liposomes modified with anti-CXCR4 antibodies on the surface, encapsulating Lcn2 siRNA for targeting MBC cells and for blocking the migration along CXCR4-CXCL12 axis in breast cancer." (PMID 33916786, 2021).